UPP2 (uridine phosphorylase 2)
Description:
Catalyzes the reversible phosphorylytic cleavage of uridine to uracil and ribose-1-phosphate which can then be utilized as carbon and energy sources or in the rescue of pyrimidine bases for nucleotide synthesis. Shows broad substrate specificity and can also accept deoxyuridine and other analogous compounds.
Synonyms: UPASE2; UP2; UDRPASE2
Tractability: Small molecule: a structure with a bound ligand is known; it has a high-quality binding pocket.
Gene: Protein-coding gene on chromosome 2 (157,876,557 to 158,136,154, forward strand). Ensembl gene ENSG00000007001.
Subcellular location (Human Protein Atlas): Nucleoplasm; Mitochondria; Vesicles
Pathways (Reactome):
Metabolism: Pyrimidine catabolism; Pyrimidine salvage
Gene Ontology:
Molecular function: deoxyuridine phosphorylase activity; identical protein binding; protein binding; pyrimidine-nucleoside phosphorylase activity; thymidine phosphorylase activity; uridine phosphorylase activity; catalytic activity; pentosyltransferase activity
Biological process: dCMP catabolic process; dTMP catabolic process; dUMP catabolic process; UMP catabolic process; uridine catabolic process; xenobiotic catabolic process; nucleoside metabolic process; uridine metabolic process; CMP catabolic process; nucleotide catabolic process; UMP salvage
Cellular component: type III intermediate filament; cytosol; cytoplasm
Genetic constraint (gnomAD): Loss-of-function variants: 18 observed, 24.31 expected, observed/expected ratio (o/e) 0.74, 90% interval 0.51 to 1.1. The upper end of that interval is the gene's LOEUF score, 1.1, which puts it in group 4 of 6, group 1 being the genes least tolerant of losing a copy. Missense variants: 380 observed, 402.79 expected, observed/expected ratio (o/e) 0.94, 90% interval 0.87 to 1.03. Synonymous variants: 122 observed, 145.13 expected, observed/expected ratio (o/e) 0.84, 90% interval 0.73 to 0.98.
Homologues: Orthologues: chimpanzee UPP2 (99% identical), macaque UPP2 (96% identical), rabbit UPP2 (92% identical), guinea pig UPP2 (89% identical), mouse Upp2 (88% identical), pig UPP2 (87% identical), rat Upp2 (85% identical), tropical clawed frog upp2 (72% identical), zebrafish upp2 (65% identical), Drosophila melanogaster CG12065 (21% identical), Caenorhabditis elegans H14E04.2 (19% identical). Paralogues in human: UPP1 (61% identical).
Diseases named in the same sentence as UPP2 in open-access papers:
UPP2 is named in the same sentence as 13 diseases in open-access papers, as found by Europe PMC text mining. Sharing a sentence is not in itself a finding about the gene and the disease. The quoted sentences say what the papers report.
atherosclerosis (1 paper, 2014). A disease characterized by the build-up of fatty material and calcium deposition in the arterial wall resulting in partial or complete occlusion of the arterial lumen. "Using PheGenI, we found an eQTL overlapping Upp2 (uridine phosphorylase 2) that is associated with several phenotypes, including cardiovascular disease, atherosclerosis, stroke and obesity." (PMID 25542004, 2014).
autism (1 paper, 2015). Persistent deficits in social interaction and communication and interaction as well as a markedly restricted repertoire of activity and interest as well as repetitive patterns of behavior. "For example, modeling sex/gender-differential effects in a genome-wide association study (GWAS) reveals autism risk loci at RyR2 and UPP2 in multiplex families." (PMID 25524786, 2015).
colorectal tumors (1 paper, 2016). "UPP2 transcript expression was below the limit of quantification in both testing and validation II sets suggesting that this gene is completely silenced in colorectal tumors and corresponding adjacent mucosa tissues regardless clinical characteristics." (PMID 27733154, 2016).
Glucose intolerance (1 paper, 2025). Glucose intolerance (GI) can be defined as dysglycemia that comprises both prediabetes and diabetes. "Increasing endogenous hepatic uridine levels by inhibiting uridine phosphorylase 2 may reduce drug-induced liver lipid accumulation, although long-term uridine consumption might promote liver lipid accumulation and exacerbate glucose intolerance." (PMID 40830362, 2025).
Hyperoxaluria (1 paper, 2023). Increased excretion of oxalates in the urine. "Furthermore, UPP2 has shown great application potential in repairing cell damage caused by hyperoxaluria." (PMID 37237881, 2023).
migraine (1 paper, 2019). "The associations of six SNPs identified from our previous study, including TRPM8 rs10166942, LRP1 rs1172113, DLG2 rs655484, GFRA1 rs3781545, UPP2 rs7565931, and GPR39 rs10803531, and migraine endophenotypes, including chronic migraine and allodynia were tested." (PMID 31842742, 2019).
pancreatic ductal adenocarcinoma (1 paper, 2021). An infiltrating adenocarcinoma that arises from the epithelial cells of the pancreas. "In this case, we first reported targeted comutation of somatic novel KANK1-ALK, UPP2 intergenic NTRK3 fusion, and pathogenetic germline BRCA1 mutation in a pancreatic ductal adenocarcinoma patient." (PMID 34671564, 2021).
tumor (3 papers, 2016 to 2026). "The present study shows for the first time that only three (DPYS, UPB1, and UPP2) out of 15 evaluated 5-FU genes, are subject to notable methylation in tumor and adjacent mucosa tissues." (PMID 27733154, 2016). "In the both testing and validation II sets, methylation exceeding the limit of quantitation was detected in DPYS, UPB1, and uridine phosphorylase (UPP2, GeneID: 151531) genes in both tumor and adjacent mucosa samples (DPYS passed the correction for multiple testing)." (PMID 27733154, 2016). "Our data complies with the results reported by this database, i.e., the highest levels in UPP2, UPB1, and DPYS (the rest of the genes below 25 %) and significantly higher methylation of DPYS in tumor compared with mucosa tissues." (PMID 27733154, 2016).
cancer (2 papers, 2015 to 2026). A tumor composed of atypical neoplastic, often pleomorphic cells that invade other tissues. "Upp2, on the other hand, is involved in pyrimidine salvage, which fuels glycolysis and enables growth of cancer cells under nutrient-limited conditions." (PMID 40721510, 2026). "Using the criteria of circadian proteomic expression, circadian expression in multiple tissues and independent gene knockdown data, we propose six genes (Por, Mtss1, Dgat2, Pim3, Ppp1r3b, Upp2) involved in metabolism and cancer for further experimental investigation." (PMID 26576534, 2015).
UPP2 also shares sentences with these, for which no sentence is quoted: cardiovascular disease (1 paper); Obesity (1); psychiatric diseases (1); Stroke (1).